CCL4L2 (C-C motif chemokine ligand 4 like 2)
Description:
Chemokine that induces chemotaxis of cells expressing CCR5 or CCR1. Inhibits HIV replication in peripheral blood monocytes that express CCR5.
Synonyms: CCL4L; AT744.2; SCYA4L; SCYQ4L2
Tractability: Antibody: UniProt places it where antibodies can reach, with medium confidence; UniProt predicts a signal peptide or a membrane-spanning region.
Gene: Protein-coding gene on chromosome 17 (36,210,924 to 36,212,878, forward strand). Ensembl gene ENSG00000276070.
Subcellular location: Secreted
Pathways (Reactome):
Signal Transduction: G alpha (i) signalling events
Gene Ontology:
Molecular function: protein binding; CCR chemokine receptor binding; chemokine activity
Biological process: antimicrobial humoral immune response mediated by antimicrobial peptide; chemokine-mediated signaling pathway; eosinophil chemotaxis; inflammatory response; positive regulation of cell migration; immune response
Cellular component: extracellular region
Genetic constraint (gnomAD): Loss-of-function variants: 2 observed, 4.18 expected, observed/expected ratio (o/e) 0.48, 90% interval 0.19 to 1.45. That is too few expected variants to judge how well the gene tolerates losing a copy. Missense variants: 53 observed, 71.27 expected, observed/expected ratio (o/e) 0.74, 90% interval 0.6 to 0.94. Synonymous variants: 29 observed, 28.53 expected, observed/expected ratio (o/e) 1.02, 90% interval 0.76 to 1.39.
Homologues: Orthologues: macaque CCL4L1 (91% identical), rat Ccl4 (78% identical), mouse Ccl4 (76% identical), chimpanzee CCL4L2 (74% identical), zebrafish ccl35.1 (36% identical), zebrafish ccl35.2 (36% identical). Paralogues in human: CCL4 (97% identical), CCL3L3 (59% identical), CCL3 (55% identical), CCL5 (45% identical), CCL14 (43% identical), CCL18 (43% identical), CCL23 (41% identical), CCL11 (40% identical), CCL15 (40% identical), CCL13 (39% identical), CCL21 (39% identical), CCL16 (38% identical), and 14 more.
Diseases named in the same sentence as CCL4L2 in open-access papers:
CCL4L2 is named in the same sentence as 43 diseases in open-access papers, as found by Europe PMC text mining. Sharing a sentence is not in itself a finding about the gene and the disease. The quoted sentences say what the papers report.
psoriasis (7 papers, 2011 to 2022). An autoimmune condition characterized by red, well-delineated plaques with silvery scales that are usually on the extensor surfaces and scalp. "Cells within a single CD8 TEM cluster enriched among PSO subjects (cluster 11) showed a strong upregulation of CCL4, a CD8+ T cell recruiting chemokine associated with psoriasis, along with other inflammatory cytokines and chemokines (TNF, IFNG, CCL3, CCL4L2)." (PMID 35309349, 2022). "An increment of ≥3 copies in the CNVs of CCL4/CCL4L is associated with psoriasis severity, whereas moderate disease correlated with a lower CNV (≤2 copies); specifically, the CCL4L1 allele frequency is higher in severe psoriasis, whereas CCL4L2 is more frequent in patients with milder disease." (PMID 36143237, 2022). "CCL4L2, a ligand for CCR1 and CCR5 on macrophages and monocytes, is a polymorphism of CCL4L1, itself a non-allelic copy of CCL4 that differs in a single amino acid and all of which are associated with psoriasis severity." (PMID 29534074, 2018). "CCL4L2 and CCL22 are pivotal chemokines in patients with psoriasis to stimulate the chemotactic infiltration of dendritic cells and macrophages." (PMID 34054833, 2021).
asthma (4 papers, 2013 to 2024). "Elevated CCL4L2 expression in neutrophils is associated with inhaled corticosteroids in patients with asthma." (PMID 39361432, 2024). "In total, 6 genes were upregulated (e.g. CCL3L1, CCL4L2, GPR82) and 20 were downregulated (e.g. JUN, IFITM3, DUSP1, GNG7) in peripheral eosinophils of COPD patients compared to asthma." (PMID 39422548, 2024). "Neutrophil-produced CCL4L2 was negatively related to inhaled corticosteroid (ICS) responsiveness in asthmatics and has been suggested as a potential therapeutic target for ICS-refractory asthma." (PMID 38416332, 2024).
COVID-19 (3 papers, 2020 to 2022). A disease caused by infection with severe acute respiratory syndrome coronavirus 2. "In this study, we revealed that cytokine storms released by macrophages promoted TEX via CCL2-CCR2, CCL3-CCR1, CCL3-CCR5, CCL4-CCR5, CCL4L2-VSIR, and CCL3L1-CCR1 axes, that are associatied with poor prognosis of COVID-19." (PMID 35694714, 2022). "Further, we found that cytokine–receptor interaction axes (e.g. CCL2-CCR2, CCL3-CCR1, CCL3-CCR5, CCL4-CCR5, CCL4L2-VSIR, and CCL3L1-CCR1) observed in severe COVID-19 were significantly correlated with TEX." (PMID 35694714, 2022). "The co-expression of cytokine and receptor genes (CCL2-CCR2,CCL3-CCR1, CCL3-CCR5,CCL4-CCR5, CCL4L2-VSIR, and CCL3L1-CCR1) confirmed that cytokine–receptor axes found in COVID-19 may also play a critical role in TEX of LUSC." (PMID 35694714, 2022). "Chemokines such as CCL4L2, CCL3, and CCL4 and their respective receptors were also found to be enriched in severe-stage monocytes, indicating the potential of targeting these cytokines and/or their receptors with drugs for treating severe-stage COVID-19 patients." (PMID 32764665, 2020).
glioma (2 papers, 2022 to 2024). A benign or malignant brain and spinal cord tumor that arises from glial cells (astrocytes, oligodendrocytes, ependymal cells). "Similar pattern was observed in the expression level of FOS in the malignant glia clusters 0, 2 and CCL4L2 between the subcluster 0, 3, suggesting these genes might be vitally implicated in the progression of certain type of glioma malignant cells." (PMID 39033204, 2024).
Insulin resistance (2 papers, 2016 to 2017). Increased resistance towards insulin, that is, diminished effectiveness of insulin in reducing blood glucose levels. "Our data suggest that PT has the potential to regulate insulin resistance and metabolic syndrome by lowering the mRNA expression of PDPK-1, CCR4, CCR6, and CCL4L2 in PBMCs." (PMID 27869712, 2016).
cholangiocarcinoma (1 paper, 2020). A carcinoma that arises from the intrahepatic biliary tree (intrahepatic cholangiocarcinoma) or from the junction, or adjacent to the junction, of the right and left hepatic ducts (hilar cholangiocarcinoma). "In contrast, mononuclear phagocytes exhibited up‐regulation of chemokines such as CCL4, CCL4L2, and CCL3L3 in the cholangiocarcinoma samples and extracellular remodeling genes such as MMP19, MMP12, and HS3ST2 in the metastatic patients." (PMID 33332768, 2020).
colitis (1 paper, 2024). Inflammation of the colon. "Thus, targeting the CCL4L2‐VSIR pathway can be exploited for broad applications in colitis and IBD." (PMID 38889269, 2024).
cyst (1 paper, 2022). A sac-like closed membranous structure that may be empty or contain fluid or amorphous material. "The chemokine profile is different compared to trophozoites, the main up-regulated chemokines are the same, but CCL4, CCL4L2, CSF1, CCL5, CXCL5, and CX3CL1 are more highly up-regulated in the cyst interaction." (PMID 35573800, 2022).
gastric cancer (1 paper, 2025). A primary or metastatic malignant neoplasm involving the stomach. "In subsequent experiments, we will further elucidate the mechanism by which the VSIR gene enables gastric cancer cells to generate immune escape and promote the formation and metastasis of gastric cancer through CCL4L2." (PMID 39391750, 2025).
Hypertension (1 paper, 2022). The presence of chronic increased pressure in the systemic arterial system. "Meanwhile, we found that C5AR1, CCL4L2, CCL4, CCL20, CD163, CXCL3, and CXCL12 were only expressed in disease a, suggesting the recruitment of inflammatory factors and promotion of the inflammatory response were both more obvious in hypertension-induced AD." (PMID 35800890, 2022).
lung carcinoma (1 paper, 2025). "CD44, GIMAP4, CD69, and CCL4L2 were among the most relevant contributing markers defining the predictive ML signatures on lung cancer samples." (PMID 40989699, 2025).
osteosarcoma (1 paper, 2023). A usually aggressive malignant bone-forming mesenchymal neoplasm, predominantly affecting adolescents and young adults. "More interesting, we found many immune-related genes (including CCL3, CCL4, CCL4L2, and CXCL5) enriched in the thrombus samples of osteosarcoma, which indicates that multiple genes involved in immunological pathways may be activated concordantly." (PMID 37244923, 2023).
peripheral vertigo (1 paper, 2025). "In conclusion, our study highlights the differential inflammatory profiles in central and peripheral vertigo patients, with CCL4L2 emerging as a promising biomarker for diagnostic differentiation." (PMID 40761541, 2025). "This study aimed to explore the differential expression of CCL4L2 in the serum of patients with central and peripheral vertigo and assess its diagnostic potential." (PMID 40761541, 2025). "The diagnostic utility of CCL4L2 was further supported by ROC curve analysis, which demonstrated high sensitivity and specificity (AUC = 0.909) in distinguishing between central and peripheral vertigo." (PMID 40761541, 2025). "We measured the expression levels of CCL4L2 in the serum of 90 patients with central vertigo and 90 patients with peripheral vertigo." (PMID 40761541, 2025). "The higher expression of CCL4L2 in central vertigo patients may reflect the activation of CNS immune responses, which are more pronounced compared to peripheral vertigo." (PMID 40761541, 2025). "CCL4L2, a chemokine involved in immune cell recruitment, was significantly upregulated in central vertigo patients compared to peripheral vertigo patients." (PMID 40761541, 2025). "Furthermore, the ROC curve analysis revealed that CCL4L2 exhibited a high level of sensitivity and specificity in distinguishing between central and peripheral vertigo (p < 0.001, AUC = 0.909, sensitivity value = 0.844, specificity value = 0.800, 95% CI: 0.867–0.950)." (PMID 40761541, 2025). "CCL4L2 may serve as a potential biomarker for differentiating central from peripheral vertigo." (PMID 40761541, 2025).
Vertigo (1 paper, 2025). An abnormal sensation of spinning while the body is actually stationary. "Further research is warranted to explore the clinical utility of CCL4L2 and its potential as a therapeutic target in vertigo management." (PMID 40761541, 2025). "The results demonstrated that CCL4L2 expression was significantly higher in the central vertigo group compared to the peripheral vertigo group." (PMID 40761541, 2025). "Additionally, the functional role of CCL4L2 in vertigo pathophysiology requires further investigation, including in vivo and in vitro experiments to elucidate its mechanisms of action." (PMID 40761541, 2025). "This indicates that CCL4L2 could serve as a potential biomarker for differentiating these two types of vertigo, which is clinically significant given the challenges in accurate diagnosis." (PMID 40761541, 2025). "It should also be noted that our study lacks a control group, which limits our ability to fully assess the general expression patterns of CCL4L2 in healthy individuals and determine whether the observed differences are specific to vertigo conditions." (PMID 40761541, 2025).
virus infection (1 paper, 2024). "The proinflammatory monocytes (cluster 4) expressed a special gene combination, namely, chemokine ligands, interleukins, as well as lncRNAs (e.g., CCL3L1, CCL4, CCL4L2, CXCL2) related to virus infection, inflammation, and pyroptosis." (PMID 39473904, 2024).
tumor (15 papers, 2018 to 2025). "Notably, ITGB8 + macrophages exhibited elevated levels of pro-tumorigenic markers associated with M2-like tumor-associated macrophages, including FN1, IL1β, CCL4L2, and CCL3L1." (PMID 39743547, 2025). "Macrophage 2 had enriched expression of many chemokines and ligands, including CCL4, CCL4L2, CCL3, and CCL3L1, which were involved in recruiting immune cells to promote tumor development." (PMID 36292645, 2022). "A group of cells was shown to highly express CCL4L2, CCL4, and other chemokines and their receptors as well as IL1B, indicating the function of promoting tumor growth." (PMID 36304995, 2022). "Tumor-infiltrating NK cells differentiate into two main populations with distinct profiles of chemokine gene expression: XCL1+XCL2+ NK cells and CCL3+CCL4+CCL4L2+CCL5+ NK cells." (PMID 33424862, 2020). "Using our extensive pan-cancer NK cell atlas, we were able to generate a solely NK cell-derived, tissue-residency signature (atlas-TR: PSMA2, SLC5A3, CCL4L2, CLN3, SCGB1A1, AREG), which outperformed the conventional literature-derived TR signature across tissue and tumor type." (PMID 38956379, 2024). "However, the top five downregulated genes in state 5 predominantly include members of the C-C motif chemokine ligand family (CCL3, CCL4L2, and CCL4), which augment tumor immunity by attracting lymphocytes and macrophages." (PMID 38993839, 2024). "Although blood and tumor-infiltrating NK cells express predominantly perforin and granzyme genes that are related to cytotoxicity, tumor-infiltrating NK cells upregulate XCL1, XCL2, CCL3, CCL4, CCL4L2, and CCL5 that are chemokine genes." (PMID 33424862, 2020). "We found that many chemokine-mediated interactions were specifically present in the L group, such as the CCL4L2-VSIR, FCGR2A-CXCL9, CCL3L3-CCR1, CCL3L1-CCR11, IDE-CCL23, and CXCL11-DPP4, CCL2-CCR10 pathways which suggests that tumor cells in the L group might recruit more myeloid cells." (PMID 39268081, 2024). "Notably, the C2-CD8 cluster was characterized by low expression of cytokines/chemokines (CCL3, CCL4L2, XCL1, and XCL2), which might hinder infiltration of effector CD8 T/NK cells and DCs into the peritoneum for their anti-tumor functions." (PMID 36788228, 2023).
infection (8 papers, 2008 to 2025). The state of being infected such as from the introduction of a foreign agent such as serum, vaccine, antigenic substance or organism. "Conditional medium (CM) from the EVS infection induced significant chemotaxis of macrophage migration in comparison with that of the control, which was partly attenuated by CCL4L2 neutralization." (PMID 38889269, 2024). "However, the specific mechanisms by which infection regulates CCL4L2 expression, and how CCL4L2 modulates epithelial homeostasis, remain unknown." (PMID 38889269, 2024).
cancer (7 papers, 2018 to 2024). A tumor composed of atypical neoplastic, often pleomorphic cells that invade other tissues. "Upregulated DEGs included chemokines and receptors (CCL2, CCL3L1, CCL4L2, and CX3CR1), known for their roles in recruiting myeloid-derived suppressor cells (MDSC) and prompting metastasis in certain cancer types." (PMID 38903524, 2024).
CCL4L2 also shares sentences with these, for which no sentence is quoted: HIV-1 infection (3 papers); AIDS (2); atherosclerosis (1); autoimmune disease (1); Autoimmunity (1); bacterial infections (1); biliary tract cancer (1); bladder cancer (1); breast carcinoma (1); cardiovascular disease (1); Crohn disease (1); Glycogen Storage Disease (1); hepatitis B virus infection (1); human papillomavirus infection (1); inflammatory bowel disease (1); melanoma (1); metabolic syndrome (1); mole (1); nicotine addiction (1); oral cancer (1); Parkinson disease (1); rheumatoid arthritis (1); shigellosis (1); type 1 diabetes (1); viral myocarditis (1).